AFP (alpha fetoprotein)
Diseases named in the same sentence as AFP in open-access papers (continued):
Sharing a sentence is not in itself a finding about the gene and the disease.
hepatocellular carcinoma (continued). "Alpha-fetoprotein (AFP) is produced by some tumors, such as hepatocellular carcinoma and yolk sac tumors, leading to an increase in serum AFP level." (PMID 30191347, 2018). "Hemoperitoneum due to rupture of hepatocellular carcinoma with intratumoral hemorrhage was suspected, although the serum alpha-fetoprotein and protein induced by vitamin K absence-II levels were within normal range." (PMID 29725882, 2018). "Compared with the traditional tumor biomarker of hepatocellular carcinoma, AFP, LDH has the advantages of low cost, simple operation, and rapid detection." (PMID 30687735, 2018). "There are a few reports that demonstrate that AFP assumes a fundamental role in the control of tumour development, cell separation and in mediating multiplication of human hepatoma cells, conceivably through AFP receptors." (PMID 35540326, 2018). "Exogenous AFP can not only promote the proliferation of hepatocellular carcinoma cells and the formation of tumor blood vessels, but also enhance the antiapoptosis effect of cancer cells." (PMID 29805966, 2018). "High serum AFP expression in adults generally indicates a high possibility of hepatocellular carcinoma in patients with chronic hepatitis or cirrhosis." (PMID 29854714, 2018). "Hepatocellular carcinoma (HCC) was suspected because alpha-fetoprotein (102 ng/ml) (AFP) and lectin 3 (L3) fraction (85.4%) were elevated and the appearance on enhanced computed tomography was not inconsistent with HCC." (PMID 30203247, 2018). "We conducted a comprehensive analysis to evaluate clinical utility of decarboxylation prothrombin combined with α-fetoprotein (AFP) for diagnosing primary hepatocellular carcinoma (HCC)." (PMID 29717027, 2018). "The lectin inhibited monoclonal antibody binding to fucosylated alpha-fetoprotein, an early marker of hepatocellular carcinoma." (PMID 29849005, 2018). "In another study, low MT1M expression was found to be linked to high alpha-fetoprotein (AFP) levels and high tumor recurrence rates following curative resection in patients with hepatocellular carcinoma." (PMID 30139373, 2018). "AFP is a well-recognised marker of a hepatic foetal phenotype and is also discussed as a marker of hepatocellular carcinoma." (PMID 30008028, 2018). "An over 10 times increase of AFP or a progressively increasing of APF compared to the test value are regarded to have a bigger possibility of hepatocellular carcinoma." (PMID 28178677, 2017). "Alpha-fetoprotein (AFP) is a biomarker of hepatocellular carcinoma, one of the most common malignant cancers." (PMID 28825646, 2017). "The positive rate of hepatocellular carcinoma circulating cells was above 90% in combination of GPC3 with alpha-fetoprotein." (PMID 28510121, 2017). "GPC3 was considered as important as alpha-fetoprotein in a fast and effective cell sorting strategy to specifically identify hepatocellular carcinoma circulating cells." (PMID 28510121, 2017). "For example, compared with other malignancies, alpha-fetoprotein (AFP) was specific expressed in hepatocellular carcinoma." (PMID 29152081, 2017). "This two-step transcription amplification system comprised two regulatory elements, Epo HRE and AFPL promoter (alpha-fetoprotein (AFP) promoter with enhancer regulatory region (~0.4 kbp), which has a higher hepatoma specificity than the AFP promoter alone)." (PMID 28798809, 2017). "To date, a few markers such as hepatoma-specific γ-glutamyl transferase, hepatoma-specific AFP, oncofetal antigen glypican-3, and member 3a of Wingless-type MMTV integration site family have been developed as specific biomarkers for HCC." (PMID 28881732, 2017). "For example, serum alpha-fetoprotein (AFP) has long been used as a diagnostic marker for hepatocellular carcinoma (HCC), however the value of AFP in HCC diagnosis has recently been challenged due to its significant rates of false positive and false negative findings." (PMID 28485374, 2017).
hepatocellular carcinoma (continued). "Controversies about the combination of des-gamma-carboxyprothrombin (DCP) and alpha-fetoprotein (AFP) for hepatocellular carcinoma diagnosing still exist." (PMID 29163838, 2017). "AFP is specific biomarker of hepatocellular carcinoma and synthesis in the fetal stage of germ cells." (PMID 28240047, 2017). "For hepatocellular carcinoma patients, serum concentrations of AFP, alanine transaminase (ALT) and aspartate transaminase (AST) were used to diagnose and indicate the extent of liver damage." (PMID 28969038, 2017). "Gastric hepatoid adenocarcinoma (GHAC) is an atypical form of gastric cancer (GC) that has similar tissue morphology to hepatocellular carcinoma and frequently produces alpha-fetoprotein." (PMID 28545511, 2017). "For example, AFP is currently used as the biomarker to test the existence of hepatic inflammation or hepatocellular carcinoma." (PMID 28178677, 2017). "Alpha-fetoprotein (AFP) is the most commonly used tumour marker for hepatocellular carcinoma (HCC) screening whereby patients with a high AFP level indicates a bad prognosis than patients with lower AFP levels." (PMID 29268718, 2017). "Up to now, the early screening of hepatocellular carcinoma mainly depends on liver ultrasound and alpha-fetoprotein (AFP)." (PMID 28060739, 2017). "AFP is typically expressed during development in hepatic progenitor cells or hepatocellular carcinoma cells." (PMID 28922406, 2017). "Human AFP is a protein that is specifically expressed in human hepatocellular carcinoma (HCC) cells." (PMID 27913752, 2017). "Expression of CHALV1 and AFP was markedly higher in primary hepatocellular carcinomas than in primary hepatocytes (83857)." (PMID 27756242, 2016). "For example, serum α-fetoprotein (AFP), a commonly used hepatocellular carcinoma biomarker, can be fractionated into three glycosylation patterns—L1, L2, and L3—using Lens culinaris agglutinin lectin." (PMID 27209430, 2016). "CHALV1 was raised against liver carcinoma cells of human origin and AFP is routinely used for liver cancer diagnosis." (PMID 27756242, 2016). "To confirm physiological relevancy, we detected CHALV1 and AFP in primary hepatocytes (83857) and primary hepatocellular carcinoma tumors (90768B, 34B, 647B, 108395B, and 110831B) which were isolated from liver resection specimens of liver cancer patients." (PMID 27756242, 2016). "In vivo AFP is only expressed during liver embryogenesis, in fetal liver cells, and hepatocellular carcinomas, while albumin is produced by differentiated hepatocytes in the adult liver." (PMID 27610270, 2016). "Alpha-fetoprotein is produced by a variety of tumors such as hepatocellular carcinoma, hepatoblastoma, and germ cell tumors of the ovary and testes." (PMID 27246404, 2016). "By utilizing the CSS NPs as red luminescent nanoprobes, we demonstrate the successful UCL and DSL bioassays of a typical hepatic carcinoma biomarker, alpha-fetoprotein (AFP), in human serum samples." (PMID 30155152, 2016). "Overexpression of miR-620, miR-1236 and miR-1270 in hepatoma cell line was associated with an incremental increase in binding to the specific sites of AFP mRNA 3′-UTR, as well as a decrease in AFP." (PMID 27835879, 2016). "It has been demonstrated that fucosylated alpha-fetoprotein (AFP) is more specific as a hepatocellular carcinoma biomarker than AFP itself." (PMID 27014630, 2016). "Hepatoid adenocarcinomas have been defined as AFP-producing adenocarcinomas with morphologic features similar to hepatocellular carcinoma." (PMID 27708233, 2016). "In this study, we focused on the effects of AFP on the BITC-induced inhibition of hepatoma cell growth and the migration/invasion potential, explored the effects of BITC on hepatoma cell drug resistance, metastasis and related mechanisms." (PMID 27716619, 2016). "These CTLs had greater cytotoxicity against AFP+ hepatocellular carcinoma cells than did CTLs obtained from dendritic cells in vitro and in vivo." (PMID 27007051, 2016).
hepatocellular carcinoma (continued). "The functions of miRNAs in AFP gene expression in hepatoma cells, as well as a correlation with disease and therapy, have not yet been reported." (PMID 27835879, 2016). "This retrospective cohort study aimed to evaluate the prognostic value of the alpha-fetoprotein (AFP) response in advanced-stage hepatocellular carcinoma (HCC) patients treated with sorafenib combined with transarterial chemoembolization." (PMID 26831408, 2016). "The REACH-2 trial will evaluate the efficacy and safety of ramucirumab in a global cohort of participants with hepatocellular carcinoma and elevated baseline AFP (ClinicalTrials.gov Identifier: NCT02435433)." (PMID 27776351, 2016). "Despite exposure to high plasma levels of AFP during hepatocellular carcinoma development, only low immunity is mounted against the protein." (PMID 27713135, 2016). "Alpha-fetoprotein (AFP) is the most widely used serum biomarker for hepatocellular carcinoma (HCC), despite its limitations." (PMID 26986465, 2016). "AFP also promoted malignant behaviors and antagonized the apoptosis induced by paclitaxel in hepatoma cells." (PMID 27716619, 2016). "Serum alpha-fetoprotein (AFP) has been extensively used as a biomarker for hepatocellular carcinoma (HCC) and yolk sac tumors." (PMID 26976278, 2016). "Elevated serum AFP level in adults is considered as abnormal and serum AFP level is frequently used as a suitable biomarker for diagnosing and monitoring hepatocellular carcinoma (HCC) and yolk sac tumor." (PMID 27057629, 2016). "Alpha fetoprotein (AFP) is a tumor-associated protein found in certain fetal organs, proliferating hepatocytes and certain adult cancer cells, such as hepatocellular carcinoma (HCC) cells." (PMID 27835879, 2016). "Alpha-fetoprotein (AFP) is an important marker for hepatocellular carcinoma, and the detection of serum AFP is currently the principle method for the diagnosis of hepatocellular carcinoma." (PMID 27631210, 2016). "Elevated serum AFP levels have been used mainly to predict the development of hepatocellular carcinoma, including large tumor size, advanced or metastatic stages, portal vein thrombosis, and postoperative recurrence." (PMID 27121855, 2016). "A high level of serum alpha fetoprotein (AFP) is positively associated with human hepatocellular carcinoma (HCC) carcinogenesis and metastasis; however, the function of AFP in HCC metastasis is unknown." (PMID 26756858, 2016). "AFP levels are reactivated in liver regeneration and hepatocarcinogenesis, which occur in hepatocellular carcinoma, chronic liver disease, acute or chronic viral hepatitis, and gonadal tumors." (PMID 27121855, 2016). "For decades, serum alpha-fetoprotein (AFP) is the most commonly used surveillance test for hepatocellular carcinoma (HCC)." (PMID 26784252, 2016). "Alpha-fetoprotein (AFP) stands alone in a fourth category as a biomarker of hepatocyte proliferation (e.g. liver development, hepatocellular carcinoma, liver regeneration)." (PMID 28337112, 2016). "Alpha-fetoprotein (AFP) is a marker of hepatocellular carcinoma (HCC) and serves as a target for immunotherapy." (PMID 27713135, 2016). "Serum assays of circulating AFP play an important role in the diagnosis of hepatocellular carcinoma (HCC) and monitoring responses to treatment." (PMID 26199728, 2015). "These indicate that MDK is a novel marker and superior to AFP with a lower false-positive rate in diagnosing and differentiating hepatocellular carcinomas from liver cirrhosis." (PMID 25737783, 2015). "It is different from other ovarian neoplasms that have hepatic differentiation and production of AFP and must be distinguished especially from metastasis on the ovary of hepatocellular carcinoma (HCC) and hepatoid yolk sac tumors (HYST)." (PMID 26213594, 2015). "Another common use of AFP is the confirmation and monitoring of certain pathological conditions, including hepatoblastoma, hepatocellular carcinoma, germ cell cancer and gastric cancers." (PMID 25822740, 2015).
hepatocellular carcinoma (continued). "Under certain pathological conditions, the expression of AFP is elevated and high serum concentrations are usually an indication of underlying diseases, including hepatocellular carcinoma (HCC), pancreatic and gastrointestinal carcinomas, germ cell tumours of the testis, and brain tumours." (PMID 26509158, 2015). "Despite its role as a hepatocellular carcinoma serum marker, the role of AFP in cancer growth and metabolism has been investigated, and great progresses have been made." (PMID 25822740, 2015). "While alpha-fetoprotein (AFP) is the most widely used tumour marker for hepatocellular carcinoma (HCC) surveillance, experience with des-gamma-carboxyprothrombin (DCP) is limited." (PMID 26341083, 2015). "Recently, investigation indicated that AFP activated PI3K/AKT signal pathway to promote proliferation of hepatoma cells." (PMID 25682869, 2015). "To investigate the role of telomerase inhibition on AFP secretion, we treated cells belonging to the hepatocellular carcinoma cell lines HepG2/C3A and PLC/PRF/5 with two different telomerase inhibitors, namely costunolide and BIBR1532." (PMID 25822740, 2015). "Some tumors produce AFP, including hepatocellular carcinoma, some germ cell tumors, and hepatoid carcinoma arising from several organs." (PMID 26337640, 2015). "Serum AFP is always low expressed in healthy adults, but often high expressed in nearly 75% hepatocellular carcinoma (HCC) patients with more than 500 ng/ml1." (PMID 26497223, 2015). "Several studies have shown a correlation between increased telomerase activity and the high level of AFP observed in hepatocellular carcinoma." (PMID 25822740, 2015). "A recent study showed that the concentration of AFP in the serum is a marker for assessing the response to therapy and a marker of disease progression and survival in patients with hepatocellular carcinoma." (PMID 25822740, 2015). "The third study investigated the value of AFP for the measurement of the outcome in patients with hepatocellular carcinoma after locoregional therapy." (PMID 25822740, 2015). "One clinical study of Hepatocellular carcinoma (HCC) showed that a surveillance program consisting of measurements of AFP levels and a liver ultrasound performed every 6 months resulted in a 37% reduction in mortality." (PMID 26133466, 2015). "Immunohistochemistry using AFP (a marker of hepatocellular carcinoma) and Napsin A (a marker of lung tumors) antibodies confirmed that the tumors were metastatic from liver instead of being primary." (PMID 25945838, 2015). "Clinically, AFP is one of the indicators that aids in the diagnosis of hepatocellular carcinoma (HCC), particularly for the patients with chronic liver diseases." (PMID 25624892, 2015). "From this study, it appears that DCP is more sensitive and specific than AFP in differentiating hepatocellular carcinoma from benign liver diseases among Nigerian patients with tumour sizes ≥ 3 cm." (PMID 26341083, 2015). "AFP is produced by the majority of hepatocellular carcinomas and is directly related to the severity of the disease." (PMID 25822740, 2015). "Tumour specific promoters like α-fetoprotein (AFP) to target hepatocellular carcinoma (HCC), prostate-specific antigen (PSA) to target prostate cancer and others have been used to suppress tumour growth." (PMID 26242403, 2015). "Our study showed that DCP is superior to AFP in differentiating hepatocellular carcinoma from benign liver diseases in Nigerian patients presenting with large-size tumours (≥3 cm in diameter)." (PMID 26341083, 2015). "The patient’s AFP tumor marker levels of 75.77 ng/ml and the 5-year history of hepatitis B were taken into account and the diagnosis was confirmed as hepatocellular carcinoma (HCC)." (PMID 24396445, 2014). "Elevated AFP is found in patients with primary hepatocellular carcinoma (HCC) and yolk-sac derived germ cell tumors." (PMID 28788700, 2014).
hepatocellular carcinoma (continued). "In a prior study, we had reported AFP to be more sensitive in detecting hepatocellular carcinoma than YB-1/p18." (PMID 24443788, 2014). "Alpha fetoprotein (AFP) is an oncofetal antigen over-expressed by many hepatocellular cancers (HCC)." (PMID 24708667, 2014). "It has been described that extracellular stimuli like HGF are involved in the regulation of cell proliferation in hepatocellular carcinoma, as well as in the expression of albumin and alpha-fetoprotein." (PMID 24416255, 2014). "In laboratory data, more than half the cases showed high CEA or CA19-9 with normal AFP and was diagnosed preoperatively as cholangiocarcinoma or hepatocellular carcinoma." (PMID 24475740, 2014). "The expression of alpha fetoprotein (AFP, a hepatoma marker) was detectable in all tumor tissues from mice by western blotting and immunohistochemistry (IHC), suggesting that LO2 cell line is successfully transformed by HBx and survivin." (PMID 24886421, 2014). "In hepatocellular carcinoma models, it was shown that AFP inhibited IL-12, leading to decreased cytolytic activity of NK cells, but reconstitution of IL-12 in the face of elevated AFP reversed these effects." (PMID 24497984, 2014). "The hepatoma cells HuH-7 and HepG2 cells are known to secrete a large and a low amount of AFP, respectively." (PMID 25105025, 2014). "AFP is a liver specific glycoprotein that expresses primarily at the foetal liver and the placenta, and since it overexpresses in 60%–70% of hepatocellular carcinoma cells, is used as a tumor marker in hepatocarcinoma diagnosing." (PMID 24416255, 2014). "PDIA3 expression in hepatocellular carcinoma is positively correlated with tumor grade and alpha-fetoprotein (AFP) level." (PMID 23782473, 2013). "In clinical practice, AFP is often used as a tumor marker of hepatocellular carcinoma and yolk sac tumors." (PMID 23382965, 2013). "The purpose of this was to specifically identify one or more proteins that are able serve as biomarkers for predicting a pathogenic condition and for prognostic purposes, similar to α-fetoprotein (AFP) for hepatocellular carcinoma (HCC)." (PMID 24223640, 2013). "The expressions of zinc fingers and homeoboxes 2, nuclear factor-YA, and alpha-fetoprotein mRNA in 63 hepatocellular carcinoma were detected by reverse transcriptase-polymerase chain reaction and compared with the clinical parameters of the patients." (PMID 23533382, 2013). "A hepatoma-specific band of serum GGT-II has been determined to be an effective tumor marker complementary to AFP for the diagnosis of HCC." (PMID 24137480, 2013). "All data obtained so far indicate a functional usage of the hCMV/AFP hybrid promoter element with satisfactory specificity and sensitivity for hepatocellular carcinomas." (PMID 23734827, 2013). "Alpha-fetoprotein (AFP) and des-gamma-carboxy prothrombin (DCP) have been used as diagnostic tools for hepatocellular carcinoma (HCC)." (PMID 23282286, 2013). "The alpha-fetoprotein (AFP)-L3 fraction, which is fucosylated AFP, has also been used clinically as a tumor marker for hepatocellular carcinoma since 1996 in Japan and since 2005 in the United States." (PMID 23922970, 2013). "For two other common tests, alpha-fetoprotein (AFP) for hepatocellular carcinoma and CA15-3 (mucin 1 epitope) for breast cancer, specific glycan structures on these proteins are monitored." (PMID 23390961, 2013). "A tissue-specific AFP-dependent expressing pEPito derivate achieved liver carcinoma specific expression in vitro and in vivo." (PMID 23734827, 2013). "AFP is a clinically useful and reliable marker for the diagnosis of primary hepatocellular carcinoma, hepatoblastoma and yolk-sac tumors." (PMID 23833646, 2013). "Paul Hallenbec have pioneered the efforts in this direction by using α-fetoprotein (AFP) promoters to drive the adenovirus E1A gene to treat hepatocellular carcinoma." (PMID 22321574, 2012).